ALDH2 (aldehyde dehydrogenase 2 family member)
Diseases named in the same sentence as ALDH2 in open-access papers (continued):
Sharing a sentence is not in itself a finding about the gene and the disease.
gastric cancer (continued). "In a study from Poland, the same ALDH2 variant was found to be associated with a 2.3-fold risk of stomach cancer among daily drinkers and 3-fold risk was reported among those with 40 or more drink-years." (PMID 22242613, 2012). "A relative risk of 3.5 for stomach cancer has been reported among ALDH2-deficient Japanese heavy drinkers." (PMID 22242613, 2012). "ALDH2 gene polymorphisms were found to modify the susceptibility to the development of gastric cancer associated with alcohol intake, especially in case of the ALDH2 *1/*2 genotype." (PMID 22838407, 2012). "However, both the less active ADH1B*1 allele and inactive ALDH2*2 allele carriers demonstrated an increased risk of synchronous gastric cancers (OR, 1.77; 95% CI, 1.03–3.04)." (PMID 39063094, 2024). "Furthermore, moderate or heavy drinking increased the gastric cancer risk in inactive ALDH2*2 allele carriers (OR, 2.23; 95% CI, 1.63–3.05) more than in active ALDH2*1/*1 carriers (OR, 1.40; 95% CI, 0.98–2.01)." (PMID 39063094, 2024). "In contrast, recent large case‐control studies (>1000 cases each) in South Korea and Japan showed that ALDH2‐rs671 AA and AG genotypes were associated with 22% to 30% lower risk of colorectal cancer, but approximately 23% to 30% higher risk of stomach cancer, compared to GG genotype." (PMID 35048370, 2022). "Furthermore, it has already been reported that the ALDH2 p.E504K variation is associated with the risk of esophageal and stomach cancers in East Asia." (PMID 34073884, 2021). "Helicobacter pylori, atrophic gastritis, alcohol consumption, tobacco smoking, acid-suppressive drugs, ALDH2-deficiency associated with alcohol consumption, pickled foods, fermented soy foods, and some fermented dairy products are risk factors for stomach cancer." (PMID 29303995, 2018). "Notably, ALDH2 A allele carriers who drink ≥150 g/week have an increased risk of gastric cancer (OR = 2.08, 95% CI = 1.05–4.12) relative to GG genotype carriers who drink 0 to <150 g/week (p for interaction = 0.08)." (PMID 28538665, 2017). "However, consideration of the ALDH2 genotype is essential in further evaluations of the relationship between alcohol consumption and H. pylori infection and their joint effect on the gastric cancer risk." (PMID 28036260, 2017). "Our meta-analysis assessed the association of the ALDH2 rs671 G>A polymorphism, alcohol drinking and GC risk with seven case-control studies and showed that the risk of stomach cancer among drinkers was increased by 1.4-fold compared with that among non-drinkers." (PMID 29254255, 2017). "Their study showed a significantly increased risk for GC associated with the ALDH2 rs671 G>A polymorphism, but there were only three case-control studies analysing the relationship between the ALDH2 rs671 G>A polymorphism and stomach cancer in the stratified analysis." (PMID 29254255, 2017). "The SNP we identified on ALDH2 (rs16941667) is associated with increased risk for gastric cancers." (PMID 26111525, 2015). "Tryptophan Metabolism-associated Genes (TMGs), such as ECHS1 and ALDH2, are crucial in cancer progression through immunosuppressive mechanisms, particularly in Gastric Cancer (GC)." (PMID 39328412, 2024). "From this perspective, we hypothesized that an East Asian-specific interaction between H. pylori infection and alcohol consumption on the gastric cancer risk may occur in this region where the ALDH2 rs671 polymorphism is prevalent, thereby causing the excessive gastric cancer incidence." (PMID 28036260, 2017). "In a more recent Japanese study including 45 alcoholics with gastric cancer and 281 controls, the odds ratio (OR) for those with severe corpus AG in combination with ALDH2 deficiency was 39 as compared with an OR of 18 for those with AG alone and OR of 10 for those with the ALDH2 deficiency alone." (PMID 22242613, 2012).
gastric cancer (continued). "Parallel to increased local ACH exposure, the risk of ALDH2-deficient alcohol drinkers for oral, pharyngeal, esophageal, and gastric cancer is manifold compared to alcohol-consuming individuals with the active ALDH2-enzyme." (PMID 29303995, 2018). "“ALDH2 and ADH1 Genetic Polymorphisms May Contribute to the Risk of Gastric Cancer: A Meta-Analysis” published in PloS one was retracted due to error in methods, fake peer review and paper mill." (PMID 38984306, 2024). "In contrast, a recent large-scale prospective cohort study from China revealed no increased risk of gastric cancers in both ALDH2*1/*2 and ALDH2*2/*2 carriers." (PMID 39063094, 2024). "To date, the relationship between the aldehyde dehydrogenases-2 (ALDH2) rs671 G>A (Glu504Lys) polymorphism and gastric cancer (GC) risk has not been thoroughly elucidated." (PMID 29254255, 2017). "The recent meta-analysis suggests that ALDH2 and ADH1 genetic polymorphisms may play crucial roles in the pathogenesis of gastric cancer." (PMID 28538665, 2017). "The effect of alcohol consumption on the risk of gastric cancer (GC) has not yet been fully elucidated, and an aldehyde dehydrogenase 2 (ALDH2) polymorphism, rs671, is a genetic variant that influences alcohol consumption in East Asians." (PMID 28036260, 2017). "Thus, combination of H. pylori-derived CAG and ALDH2*1/2*2 exacerbated the progression to gastric carcinoma (OR = 39.2 for severe CAG plus ALDH2*1/2*2)." (PMID 28538665, 2017). "On the other hand, several other studies have reported increased incidences of gastric cancer among ALDH2-deficient nondrinkers and as well as among high consumers of foodstuffs produced by fermentation." (PMID 25831092, 2015). "In addition, ADH2 and ALDH2 polymorphism and alcohol drinking do not appear to be linked each other for the development of stomach cancer in Chinese males." (PMID 28538665, 2017).
colorectal cancer (26 papers, 2002 to 2026). A primary or metastatic malignant neoplasm that affects the colon or rectum. "Although a few studies found that genetic polymorphisms in the ALDH2 were associated with colorectal cancer risk, genetic variants in the alcohol metabolic genes have not been systematically explored for the susceptibility for this cancer." (PMID 32377192, 2020). "In view of the uncertain association between ALDH2 Glu487Lys polymorphism and colorectal cancer risk, we sought to obtain more precise information by conducting a meta-analysis including all of the evidence produced to date." (PMID 24558407, 2014). "A number of studies have explored the association of the aldehyde dehydrogenases-2 (ALDH2) Glu487Lys polymorphism and risk of colorectal cancer; however, the results are inconsistent." (PMID 24558407, 2014). "In conclusion, this comprehensive meta-analysis has evaluated all published data currently available on the ALDH2 Glu487Lys polymorphism and risk of colorectal cancer." (PMID 24558407, 2014). "The present hospital based case-control study in Japan was conducted to evaluate the gene-environment interaction between alcohol and ALDH2 polymorphism for the risk of colorectal cancer." (PMID 12033531, 2002). "Some ALDH2*2 carriers continue to consume alcohol despite experiencing these adverse effects, placing them at higher risk for several diseases, including esophageal, head and neck, liver, and colorectal cancers, as well as cardiovascular disease." (PMID 41324337, 2026). "The genetic polymorphisms in ALDH2 were reported to be associated with colorectal cancer." (PMID 32377192, 2020). "Two recent meta-analyses indicate that ALDH2 Glu504Lys SNP may be associated with a decreased risk of colorectal cancer." (PMID 26491656, 2015). "Characteristics of studies included in ALDH2 Glu487Lys polymorphism and colorectal cancer." (PMID 24558407, 2014). "Our results suggested that the ALDH2 Glu487Lys polymorphism may be associated with a decreased risk of colorectal cancer." (PMID 24558407, 2014). "Thus, there is a distinct possibility that the ALDH2 polymorphism could impact on the risk of colorectal cancer." (PMID 12033531, 2002). "In Korea, a case-control study of alcohol dehydrogenase 1B (ADH1B) (rs1229984) and aldehyde dehydrogenase 2 (ALDH2) (rs671), which are well-known genes that affect drinking behavior, and colorectal cancer was reported." (PMID 37641821, 2023). "Silencing of ALDH2 decreased PD-L1 protein and enhanced TILs infiltration in colorectal cancer cells." (PMID 36733484, 2023). "In other words, ADH1B and ALDH2 genotypes can be candidates for consideration of personalized prevention of colorectal cancer by aspirin." (PMID 36923554, 2022). "ADH1B and ALDH2 genotypes can be the markers for the personalized prevention of colorectal cancer by aspirin." (PMID 36923554, 2022). "Recently, several researchers have found that ALDH2 mediates the immune evasion induced by alcohol in colorectal cancer by stabilizing the expression of PD-L117." (PMID 35169188, 2022). "A harmful effect of heavy drinking on colorectal cancer has been suggested by observational studies as well as an MR study using the ALDH2 genotype as a marker of alcohol exposure." (PMID 32701947, 2020). "Accordingly, previous studies have commonly focused on ADH1B, ADH1C, ALDH2, CYP2E1, and MTHFR genotypes as modifiers of the association between alcohol consumption and risk of alcohol-related cancers, including colorectal cancer." (PMID 29464080, 2018). "Overall, the role of ALDH2*2 in the development of colorectal cancer is inconclusive and all of the studies conducted to date have a small sample size that resulted in insufficient statistical power and lack of precision." (PMID 28253921, 2017). "Chiang's study found that the allele frequency of ALDH2 A was significantly higher in colorectal cancer cases; however, Miyasaka's study found that the A/A genotype of ALDH2 might not be a risk factor for colorectal cancer." (PMID 24558407, 2014).
colorectal cancer (continued). "The detrimental effects of heavy drinking on colorectal cancer were suggested by studies using the COLCA1/COLCA2 and ALDH2 genotypes as indicators of alcohol exposure." (PMID 39311360, 2024). "Metabolites of ALDH2, such as acetaldehyde and 4-HNE, have been proven to influence the clinical characteristics of liver cancer, colorectal cancer, breast cancer and upper aerodigestive tract cancer by regulating DNA methylation levels." (PMID 35517510, 2022). "MiR-1, a key regulator of ALDH2 and PPAP2C in path:00561_1, is involved in the development of many cancers, including bladder, liver, lung, prostate, and colorectal cancer." (PMID 26472186, 2015). "SNPs from ADH1B and ALDH2 genes, included in alcohol metabolism pathway, were genotyped in 1694 CRC cases and 1851 matched controls from the Molecular Epidemiology of Colorectal Cancer study." (PMID 24282520, 2013).
atherosclerosis (24 papers, 2016 to 2026). A disease characterized by the build-up of fatty material and calcium deposition in the arterial wall resulting in partial or complete occlusion of the arterial lumen. "Our results show that the abnormal expression of genes such as CD36 and ALDH2 is closely associated with the development of atherosclerosis." (PMID 41287052, 2025). "Interfering with macrophage ALDH2 expression can significantly improve atherosclerosis, suggesting that ALDH2 deficiency plays a protective role in atherosclerosis." (PMID 40968356, 2025). "In summary, these findings indicate that the role of ALDH2 deficiency and ALDH2 dysfunction in atherosclerosis is distinct and closely related to the type of tissue and cell." (PMID 40968356, 2025). "The inhibition of ALDH2 expression in macrophages can inhibit their capacity for efferocytosis and promote atherosclerosis, indicating that ALDH2 deficiency promotes atherosclerosis." (PMID 40968356, 2025). "The rs671 polymorphism in ALDH2 promotes macrophage foam cell formation and vascular inflammation in atherosclerosis." (PMID 34764958, 2021). "Large scale multi-centered RCT studies are still warranted to understand the interplay between ALDH2 polymorphism and atherosclerosis." (PMID 27191745, 2016). "Clinical studies highlight ALDH2 rs671 mutation as a common risk factor for atherosclerotic cardiovascular diseases, where macrophage ALDH2 stabilizes Rac2 to facilitate efferocytosis and reduce atherosclerosis development." (PMID 39660125, 2024). "ALDH2 is the best studied subunit of this family and it was suggested to exert a protective role in the endothelium against age-associated dysfunctions to prevent atherosclerosis." (PMID 37649604, 2023). "Therefore, targeting ALDH2 expression in a tissue-specific manner or correcting ALDH2 functional mutation in a cell-specific manner might be a therapeutic option to balance the dual role of ALDH2 in atherosclerosis." (PMID 40968356, 2025). "This polymorphism, which reduces ALDH2 enzymatic activity to 1%–6% of the wild‐type, is associated with a spectrum of cardiovascular pathologies, including ACS, MI, and atherosclerosis." (PMID 41551908, 2026). "miR-193b-3p can aggravate endothelial cell injury in atherosclerosis by downregulating ALDH2 expression and exacerbating ER stress-related apoptosis." (PMID 40968356, 2025). "It has been reported that macrophage expression of ALDH2 is conducive to limiting the persistent inflammation during atherosclerosis through the inhibition of Rac2 degradation and the promotion of macrophage efferocytosis." (PMID 40968356, 2025). "Early screening for mutations in the ALDH2 and MTHFR genes should be done in people who have already found single atherosclerosis." (PMID 37355582, 2023). "By using RNA-seq, proteomics, and immunoprecipitation experiments, we later discovered and verified Rac2 as its downstream target, demonstrating the crucial function of the ALDH2-Rac2 axis in mediating cytokinesis during atherosclerosis." (PMID 36588568, 2022). "Acetaldehyde and lipid aldehyde can cause atherosclerosis through the formation of protein byproducts, and ALDH2 play a role in anti-atherosclerosis via its detoxication." (PMID 28894224, 2017). "The extent of atherosclerosis in Lv-GFP group was intermediate between that observed in the Lv-ALDH2-overexpression and Lv-ALDH2-RNAi groups." (PMID 27191745, 2016). "Interestingly, ALDH2rs671 in macrophages can accelerate Rac2 degradation and promote the AMPK-mediated phosphorylation of ALDH2 to aggravate atherosclerosis." (PMID 40968356, 2025). "Therefore, study of the regulatory mechanism of ALDH2 on NLRP3 will provide new ideas for the treatment of atherosclerosis." (PMID 36910525, 2023).
atherosclerosis (continued). "One earlier study from our group demonstrated that ALDH2 mutation is associated with decreased high-density lipoprotein cholesterol (HDL-C) levels, suggesting that ALDH2 might influence atherosclerosis progression and subsequently CAD via lipid accumulation." (PMID 27191745, 2016). "Whether ALDH2 can also play such a role in macrophages in atherosclerosis remains to be explored." (PMID 36910525, 2023). "In the early stage of life, ALDH2 mainly sustains cell protein homeostasis by reducing unfolded or misfolded protein production, and thus the activation of ALDH2 could decelerate the progression of diseases such as atherosclerosis via decreasing ERS and apoptosis." (PMID 33411685, 2020). "Despite studies confirming that ALDH2 can negatively regulate NLRP3 inflammasome and delay the development of atherosclerosis, the mechanisms involved are still poorly understood." (PMID 36910525, 2023). "However, macrophage ALDH2 expression can also contribute to atherosclerosis, as AMPK-phosphorylated ALDH2 was confirmed to result in impaired lysosomal function, blocked autophagy, increased lipid deposition, and accelerated foam cell formation." (PMID 40968356, 2025). "A recent study using ALDH2 KO mice revealed that ALDH2 regulates foam cell formation through interactions with LDL receptors and 5’ adenosine monophosphate-activated protein kinase (AMPK) pathway, providing a new molecular mechanism for ALDH2 in atherosclerosis." (PMID 30413026, 2018).